IL4R (interleukin 4 receptor)
Description:
Receptor for both interleukin 4 and interleukin 13. Couples to the JAK1/2/3-STAT6 pathway. The IL4 response is involved in promoting Th2 differentiation. The IL4/IL13 responses are involved in regulating IgE production and, chemokine and mucus production at sites of allergic inflammation. In certain cell types, can signal through activation of insulin receptor substrates, IRS1/IRS2. Soluble IL4R (sIL4R) inhibits IL4-mediated cell proliferation and IL5 up-regulation by T-cells.
Synonyms: IL-4RA; CD124; IL4RA
Tractability: Antibody: an approved drug acts on it; its Gene Ontology location is reachable by antibodies, with high confidence; UniProt places it where antibodies can reach, with medium confidence; UniProt predicts a signal peptide or a membrane-spanning region; the Human Protein Atlas places it where antibodies can reach. PROTAC: ubiquitination databases record sites on it. Other modalities: a drug acting on it is in phase 2 or 3 trials.
Target class: Secreted protein
Gene: Protein-coding gene on chromosome 16 (27,313,462 to 27,364,811, forward strand). Ensembl gene ENSG00000077238.
Subcellular location: Cell membrane; Secreted (Isoform 2)
Subcellular location (Human Protein Atlas): Plasma membrane; Centriolar satellite; Nucleoplasm; Predicted to be secreted
Pathways (Reactome):
Developmental Biology: Differentiation of naive CD4+ T cells to T helper 2 cells (Th2 cells)
Immune System: Interleukin-4 and Interleukin-13 signaling
Gene Ontology:
Molecular function: interleukin-13 receptor activity; interleukin-4 receptor activity; protein binding; cytokine receptor activity
Biological process: cell surface receptor signaling pathway via JAK-STAT; interleukin-13-mediated signaling pathway; interleukin-4-mediated signaling pathway; positive regulation of tyrosine phosphorylation of STAT protein; immune response; positive regulation of cold-induced thermogenesis; positive regulation of leukocyte differentiation; signal transduction; cytokine-mediated signaling pathway; positive regulation of chemokine production; positive regulation of macrophage activation; production of molecular mediator involved in inflammatory response
Cellular component: interleukin-13 receptor complex; interleukin-4 receptor complex; plasma membrane; receptor complex; external side of plasma membrane; extracellular region; membrane
Genetic constraint (gnomAD): Loss-of-function variants: 15 observed, 38.27 expected, observed/expected ratio (o/e) 0.39, 90% interval 0.26 to 0.6. The upper end of that interval is the gene's LOEUF score, 0.6, which puts it in group 2 of 6, group 1 being the genes least tolerant of losing a copy. Missense variants: 969 observed, 1,079.3 expected, observed/expected ratio (o/e) 0.9, 90% interval 0.85 to 0.95. Synonymous variants: 400 observed, 439.84 expected, observed/expected ratio (o/e) 0.91, 90% interval 0.84 to 0.99.
Homologues: Orthologues: chimpanzee IL4R (99% identical), macaque IL4R (90% identical), pig IL4R (67% identical), dog IL4R (65% identical), guinea pig IL4R (58% identical), mouse Il4ra (52% identical), rat Il4r (52% identical), tropical clawed frog il4r (21% identical). Paralogues in human: CSF2RB (12% identical), IL9R (11% identical), IL21R (11% identical), IL2RB (11% identical), EPOR (10% identical), MPL (9% identical), IL7R (8% identical).
Diseases named in the same sentence as IL4R in open-access papers:
IL4R is named in the same sentence as 295 diseases in open-access papers, as found by Europe PMC text mining. Sharing a sentence is not in itself a finding about the gene and the disease. The quoted sentences say what the papers report.
asthma (210 papers, 2005 to 2026). "Nevertheless, the susceptibility of neutrophils for signaling through IL-4Rα should be taken in consideration in asthma therapy development." (PMID 39767651, 2024). "The anti–IL-4Rα antibody dupilumab is highly effective for treatment of severe asthma associated with eosinophilia and elevated serum IgE." (PMID 40047886, 2024). "In fact, asthma‐related IL‐4R‐encoding gene polymorphisms can promote the switching of iTreg cells to Th17 cell‐like cells, inducing the production of inflammatory factors and chemokines to modulate immune responses." (PMID 37105551, 2023). "Numerous genetic epidemiological studies have also shown that IL4 and IL4R and their gene polymorphisms play important roles in asthma in various populations." (PMID 38577257, 2023). "A study found that asthma-associated IL4R variants promoted the transformation of regulatory T cells into TH17-like cells, thereby exacerbating airway inflammation." (PMID 35586697, 2022). "Our findings suggested that G allele of IL-4R Q576R polymorphism is associated with increased risk of pediatric asthma." (PMID 36910341, 2022). "The relationship between Q576R polymorphism of IL-4 receptor (IL-4R) gene and pediatric asthma risk is still undefined." (PMID 36910341, 2022). "In conclusion, we demonstrate the significant relationship of IL-4R Q576R polymorphism with pediatric asthma." (PMID 36910341, 2022). "In conclusion, our findings showed that G allele of IL-4R Q576R polymorphism is associated with increased risk of pediatric asthma." (PMID 36910341, 2022). "This discovery was followed by more biological agents targeting key inflammatory nodes in the chronic inflammation underlying asthma, such as IL-5, IL-5R, IL-13 and IL-4R." (PMID 36561741, 2022). "Here, we performed a meta-analysis of published studies to evaluate the association between IL-4R Q576R polymorphism and risk of pediatric asthma." (PMID 36910341, 2022). "Further investigations have indicated the possible relationship of IL-4R Q576R polymorphism with pediatric asthma, however, the conclusion is drawn from studies with inadequate statistical power, sample size and clinical heterogeneity." (PMID 36910341, 2022). "Combined with our data showing TL1A is upstream of IL13, this indicates that targeting TL1A signaling offers an advantage over targeting IL13/IL4Rα or IL5 signaling in isolation to treat mucus secretion associated with asthma." (PMID 34305924, 2021). "Our previous study showed the association of IL-4, its receptor IL4Rα and IL-13 polymorphisms with asthma in the same pediatric cohort that was analyzed in this study." (PMID 34946286, 2021). "In asthma, the IL-4R variant directs the reprogramming of inducible Tregs (iTregs) to Th17-like cells in an IL-6-dependent manner." (PMID 32871353, 2020). "Another human polymorphism in IL-4Rα, in which glutamine is substituted for arginine at position 576 (IL-4RαQ576R), is associated with asthma exacerbations." (PMID 32931477, 2020). "Based on our results, we would have predicted that increased levels of IL4R result in a lower risk of asthma." (PMID 32628676, 2020). "Interleukin 4 receptor alpha (IL-4Rα) and IL-13 polymorphisms are associated with hyper IgE and asthma severity." (PMID 31824491, 2019). "This is therefore particularly important in light of recent therapeutic advances for the control of highly pathogenic cases of asthma for which IL-4Rα targeting has recently been introduced and is attracting further interest for other inflammatory conditions." (PMID 30379806, 2018). "Al Muhsen found significantly higher IL-4 receptor alpha subunit (IL-4Rα) and its single-nucleotide polymorphisms (SNPs), rs1805010 (I75V) and rs1801275 (Q576R), in Saudi asthma patients as compared to healthy subjects." (PMID 29951546, 2018).
asthma (continued). "Given the importance of IL-4Rα in triggering Th2 inflammation and the strong association between polymorphisms in this gene and asthma risk, understanding the mechanisms by which IL-4Rα expression is controlled is critical." (PMID 28721208, 2017). "Signaling via IL4Rα plays a critical role in the pathogenesis of asthma, with more than a dozen polymorphisms in the gene contributing to asthma risk." (PMID 26540410, 2015). "Depending on the IL-4R genotype, methylation of two CpG sites was associated with higher risk of asthma in 18 year olds." (PMID 26052354, 2015). "Log-linear models were used to estimate risk ratios (RRs) for asthma adjusting for uncorrelated SNPs within the IL4R gene and covariates." (PMID 23286427, 2013). "The associations between the interleukin-4 receptor α chain (IL4RA) I50V and Q551R polymorphisms and asthma risk remained controversial." (PMID 23922687, 2013). "Numerous other genes have been associated with asthma and related phenotypes, including those related to T helper cell (Th) pathways (IL-4, IL-13, IL-4Rα, TNFα and LTΑ)." (PMID 23573270, 2013). "Adjusting for multiple testing, our results suggest that DNA-M modulates the risk of asthma related to genetic variants in the IL4R gene." (PMID 23286427, 2013). "The study revealed multiple SNPs and haplotypes in LTA4H, TNFα and IL4-Rα genes which constitute risk factors for the development of difficult asthma in children." (PMID 23573270, 2013). "Although the CpG site cg09791102 is located 23,496 base pairs away from SNP rs3024685 in the intragenic region of the IL4R gene, we found that the risk of asthma is modulated by this CpG site even after adjusting for multiple testing." (PMID 23286427, 2013). "The results indicated that LTA4H A-9188>G, TNFα G-308>A and IL-4Rα A1727>G polymorphisms were significantly associated with the development of difficult asthma in paediatric patients (p<0.001, p = 0.019 and p = 0.037, respectively)." (PMID 23573270, 2013). "In this work we focus on the interleukin receptor (IL4R) gene which has been clearly established as an asthma susceptibility gene in multiple candidate gene association studies." (PMID 23286427, 2013). "A total of 12 CpG sites spanning the genomic region of the IL4R gene were analyzed for association with asthma at age 18 years." (PMID 23286427, 2013). "This is supported by previous studies which observed significant associations between IL4-Rα polymorphisms (A1199>C, T1570>C and A1727>G) and asthma-related phenotypes." (PMID 23573270, 2013). "In the present study, the haplotype ATA (of IL4-Rα A1199>C, T1570>C and A1727>G polymorphisms) was significantly more frequent in children within the difficult asthma group." (PMID 23573270, 2013). "Of the twelve CpG sites in the IL4R gene, only methylation levels of cg09791102 showed an association with asthma at age 18 years (Wilcoxon test: P = 0.01)." (PMID 23286427, 2013). "This is the first study to determine the role of both genetic and epigenetic factors within the genomic region of the IL4R gene on the risk for asthma." (PMID 23286427, 2013). "The IL-4, IL-13, and IL-4Rα interaction pathway have been implicated in the pathogenesis of AR and asthma." (PMID 22087298, 2011). "In order to track the exogenous in vivo primed T cells that we were transferring into these mice and to prevent interference of TH1 cells, we used STAT6 or IL-4Rα deficient mice on a RAG2-/- background for our asthma experiments." (PMID 22014099, 2011). "Individuals with the Ser503Pro IL4R mutation were found to have lower IgE levels and a separate study found a significant association with atopy and asthma-related phenotypes." (PMID 21867552, 2011). "After subgroup analysis by age, the ACE D/I, β2-Adrenergic Receptor (β2-AR) -79G/C, TNF-α -308G/A, Interleukin 4 receptor(IL-4R) -1902G/A and IL-13 -1923C/T polymorphisms were found significantly associated with asthma risk in Chinese children." (PMID 20868478, 2010).
asthma (continued). "In particular, in the development of increased asthma severity, investigators have reported that another combination of the ile75val IL-4Rα SNP and arg110gln IL-13 SNP has also been associated with allergy and asthma." (PMID 16503977, 2006). "This study investigates the acute and chronic effects of T2 cytokines on healthy and asthmatic bronchial epithelial cells (BECs), addressing the mechanisms underlying IL-4Rα mAb therapy in acute T2-driven inflammatory conditions and rhinoviral infection in asthma BECs." (PMID 40370530, 2025). "Our findings refine the mechanistic framework through which anti–IL-4Rα biologics, such as dupilumab, may influence viral susceptibility and post-viral inflammation in T2-high asthma." (PMID 41427379, 2025). "Furthermore, it examines the mechanisms underlying IL-4Rα mAb therapy in acute T2-driven inflammatory conditions and during rhinoviral infection in asthma BECs using a translational in vitro model of differentiated airway epithelial cells." (PMID 40370530, 2025). "Within ALL patients, the IL4R SNP rs1801275 was significantly associated with decreased asthma." (PMID 37860183, 2023). "The IL4Rα gene has also been associated with asthma in humans." (PMID 37760328, 2023). "By reducing IL-4Rα protein expression in various lung cells, including eosinophils, dendritic cells, macrophages, and airway epithelium, the modified IL-4Rα showed promise in mitigating allergic lung inflammation and airway hyperreactivity associated with asthma/allergy." (PMID 38203317, 2023). "Notably, individuals carrying one or two copies of the IL4R Glu400Ala (16-27362551-A-C) minor allele were at higher risk to suffer from allergy and asthma." (PMID 38577257, 2023). "Additionally, studies of polymorphisms in IL4R have suggested that at least some are associated both with increased prevalence of asthma and in separate cohort studies, with increased risk of colon cancer." (PMID 37860183, 2023). "Furthermore, peripheral blood eosinophilia is associated with more frequent asthma exacerbations but cannot be used to monitor the response to anti-IL-4R therapy." (PMID 38203353, 2023). "We found an association between IL-4R Q576R polymorphism and pediatric asthma risk (GG vs AA: OR = 3.75, 95% CI = 1.89–7.45; AG vs AA: OR = 2.15, 95% CI = 1.36–3.39; the dominant model: OR = 2.25, 95% CI = 1.42–3.57;the recessive model: OR = 3.05, 95% CI = 1.54–6.05)." (PMID 36910341, 2022). "Furthermore, earlier studies have revealed an IL-4/STAT-6/Tfec/IL-4Rα positive feedback regulatory loop, in which Tfec transcribes IL-4Rα expression to promote M2 programming in macrophages, which was implicated in asthma pathogenesis." (PMID 35600600, 2022). "Nevertheless, the mechanism underlying the relationship between IL-4R Q576R polymorphism and pediatric asthma risk remains unknown." (PMID 36910341, 2022). "In another research on a whole-population birth cohort, only one SNP was found correlated to one CpG region of the IL-4 receptor gene (IL-4R) whose methylation levels in whole blood of 18-year-old females showed considerable association with the risk of asthma." (PMID 33781317, 2021). "IL4R was among the significantly differentially expressed genes of the first comparison (exacerbation against controls) and is also on the list of genes previously associated with human asthma." (PMID 32998415, 2020). "Multiple polymorphism in IL-4R gene have also been identified and associated with asthma." (PMID 31866859, 2019). "Although the sample size is limited and focused on female participants, our results should generally motivate other studies to replicate the interaction we found, while also searching for new interactions between genetic variants and DNA methylation, in particular for the IL4R gene and asthma." (PMID 23286427, 2013).
asthma (continued). "Haplotype analysis also revealed two haplotypes (ATA haplotype of IL-4Rα A1199>C, IL-4Rα T1570>C and IL-4Rα A1727>G and CA haplotype of TNFα C-863>A and TNFα G-308>A polymorphisms) which were significantly associated with difficult asthma in children (p = 0.04 and p = 0.018, respectively)." (PMID 23573270, 2013). "In conclusion, we have identified multiple SNPs and haplotypes in LTA4H, TNFα and IL4-Rα genes that constitute risk factors for the development of difficult asthma in children and demonstrate combined effects which confer greater risk than that obtained for any SNP individually." (PMID 23573270, 2013). "We hypothesized that genetic variants of IL4R in interaction with DNA-M at cytosine-phosphate-guanine (CpG) sites jointly alter the risk of asthma during adolescence." (PMID 23286427, 2013). "Risk factors and IL4R markers were analyzed in respect to asthma phenotypes." (PMID 22577403, 2012). "ADAM33, FcεRIβ, RANTES, TNF-α, ACE, β2-AR, IL-4R and IL-13 genes could be proposed as asthma susceptible genes in Chinese population." (PMID 20868478, 2010). "In conclusion, we found that IL-4R Q576R polymorphism might contribute to pediatric asthma risk." (PMID 36910341, 2022). "Within IL4R, the interaction of cg26937798 with rs3024685 and with rs8832 (models 4 and 5, P = 0.003 and 0.01, respectively) indicated that increased DNA methylation of this site among subjects with the rs3024685 genotype AA or rs8832 genotype GG was associated with a lower risk of asthma." (PMID 24735657, 2014). "AZD1402 (Elarekibep) is a novel anticalin with engineered IL-4Rα antagonist binding properties that was under development for inhaled treatment of asthma." (PMID 42050192, 2026). "Virus-induced asthma exacerbations appear to involve not only the upregulation of Th2 cytokines but also an increased expression of receptors, particularly IL-4Rα, in both epithelial and CD4 + T helper cells." (PMID 41576028, 2026). "Our findings align with these observations and identify inhibition of CCL26 release from the lung epithelium as one potential mechanism of action behind the therapeutic efficacy of IL-4Rα biologics in asthma." (PMID 40370530, 2025). "Overall, they concluded that Pitrakinra, by blocking IL-4R, demonstrated clinical efficacy within defined subpopulations of uncontrolled asthma." (PMID 40564060, 2025). "Future research should address the long-term effects of anti-IL-4Rα therapy on immune tolerance and antiviral defense, as well as its clinical impact on reducing asthma exacerbations." (PMID 40370530, 2025). "Another compound, altrakincept, which is an inhaled humanized recombinant IL-4R, was used to block endogenous IL-4 in patients with asthma." (PMID 41145900, 2025). "Several loci previously associated with childhood asthma (e.g., 15q22.33, 16p12.1, and 3q21.3 near genes SMAD3, IL4R, EEFSEC, respectively) were also linked here with a more generally selected asthma." (PMID 41213931, 2025). "Dupilumab is an approved therapy for severe asthma, nasal polyposis and atopic dermatitis that inhibits IL-4 and IL-13 signaling by specifically targeting the shared IL-4Rα subunit of their respective receptor complexes." (PMID 40195539, 2025). "By reducing and normalizing key inflammatory mediators such as CCL26 and TSLP, while preserving essential antiviral defense mechanisms, IL-4Rα blockade offers a balanced approach to managing asthma symptoms and preventing exacerbations." (PMID 40370530, 2025). "A prospective phase 2 RCT comparing anti‐IL33 with itepekimab, anti‐IL4Rα with Dupi, either alone or in combination versus placebo, was performed in moderate to severe asthma patients who underwent ICS tapering." (PMID 40156481, 2025). "The synergy of dual inhibition of TSLP and IL-4Rα was also evident phenotypically in the humanized mouse asthma model." (PMID 41294800, 2025).